TNF (tumor necrosis factor)
Diseases named in the same sentence as TNF in open-access papers (continued):
Sharing a sentence is not in itself a finding about the gene and the disease.
infection (continued). "This acute phase protein is produced by the hepatocytes in response to IL2, IL1 or TNFα generated during acute infection or tissue damage." (PMID 28401944, 2017). "It is thought that MUC1 exerts anti-inflammatory effects upon infection with pathogens by suppressing pro-inflammatory cytokines such as Tumor Necrosis Factor-alpha (TNF-α)." (PMID 29268739, 2017). "Addition of TNFα to the cultures following infection induced an additional proportion of cell death that was inhibited by Nec-1, demonstrating RIPK1-dependent cell death in both cell lines in the combined presence of TNFα and M. tuberculosis infection." (PMID 28892415, 2017). "At the 1st and 3rd day, infection with A. xylosoxidans induced significant release of TNF-α, MIP-1α, IL-1α and MCP-1 in both 129sv and Alox5−/− mice." (PMID 29247243, 2017). "TNFα levels were increased after 24 h of infection with both species and were higher than TNFα produced after 4 h, whereas LPS–induced TNFα production declined from 4 h to 24 h." (PMID 28241012, 2017). "We found LPS priming can recover the expression of the repressed the cytokines (TNF-α, IL-6 and IL-1β) after Ms_PE_PGRS41 infection." (PMID 28440335, 2017). "Circulating levels of TNF-α were low, whereas levels of IL-4 were significantly increased whenever infection was present." (PMID 29348965, 2017). "Strains from both chemotypes that are deficient in β-glucanase exhibit increased recognition by dectin-1, resulting in greater amounts of TNFα and IL-6 release by murine peritoneal macrophages during infection." (PMID 29371564, 2017). "At all periods after infection analyzed, a decreased number of CD11b+ cells expressing intracellular IL-12, TNF-α, IL-1β, TGF-β, and IL-10 was detected in the lungs of IDO1−/− mice when compared to the WT counterparts." (PMID 28791025, 2017). "Infection with the mutant viruses also revealed that UL48 DUB activity and UL45 inhibit TNFα-induced NF-κB activation at late times of infection." (PMID 28570668, 2017). "The gene expression of the pro-inflammatory cytokines IL-1β, IFN-γ and TNF-α along with the anti-inflammatory cytokine IL-10 and selected chemokines were significantly up-regulated throughout infection." (PMID 28814754, 2017). "Microscopy revealed TNF−/− and etanercept-treated mice with greater mycobacteria infiltration than other groups during early and established infection (*p < 0.05 for etanercept and ***p < 0.001 for TNF−/− mice vs TNFKi, KLH, PBS, ANOVA)." (PMID 29184553, 2017). "We also found that the induction of pro-inflammatory cytokines including TNF-α, IP-10, MCP-1 and MIP-1α were associated with increased severity of infection." (PMID 28539661, 2017). "After infection with both Leishmania species, TNFα and IL-8 were down regulated in THP-1 cells depleted of IL-32γ while overexpression of IL-32γ caused a strong increase in the production of these cytokines." (PMID 28241012, 2017). "To gain insight into the systemic response to infection, we measured serum levels of the pro-inflammatory cytokines TNFα and IL-6 on day 5 after infection." (PMID 29190678, 2017). "Elevated serum viremia at day 3 post infection correlated with a strong increase in the serum concentration of pro-inflammatory cytokines, including TNF-α, MCP-1, IP-10, IL-6 and KC." (PMID 28290449, 2017). "Many cell types, especially immune cells, produce TNF in response to pathological conditions such as inflammation and infection, including: activated macrophages and T lymphocytes, natural killer (NK) cells, mast cells, and fibroblasts." (PMID 28358311, 2017). "The increase in L-arginine uptake and ARG1 activity induces polyamines production, which correlates with the increase of IL-10 and reduction of IL-12 and TNF-α levels in L. donovani THP-1-derived macrophages infection." (PMID 29379478, 2017). "LY6C+ macrophages, as a consequence of infection sensing, secrete tumor necrosis factor (TNF), which acts on local LY6C− macrophages to trigger their production of CXCL2." (PMID 28861072, 2017).
infection (continued). "Injection of anti-TNF-α neutralizing antibodies suppressed behavioral fever, and decreased fish survival in response to infection." (PMID 28182952, 2017). "P. gingivalis-infected mice produced higher amounts of IL-6 and TNF-α mRNA in the gingival tissues and GMCs, and higher protein levels in GMCs than those in sham-infected mice 1 day after the final infection." (PMID 28373699, 2017). "Following infection, TNF is expressed by a range of cells, including epithelial cells, natural killer (NK) cells, macrophages, dendritic cells (DCs), CD4+ and CD8+ T cells." (PMID 28886201, 2017). "Infection with E. coli for four hours raised the concentration of soluble TNF-α up to 2 ng/ml in supernatants of infected PBMO." (PMID 28793310, 2017). "Infection with HV-PRRSV induced a significantly higher levels of TNF-α and IL-10 in both sera and lung tissues and higher IFN-α and IFN-γ in the serum." (PMID 28839507, 2017). "We found that LPS priming of macrophages immediately prior to infection with PE_PGRS41 expressing M. smegmatis, enhances TNF-α, IL-1β and IL-6 mRNA levels and secretion." (PMID 28440335, 2017). "In serum, no changes in IL-1 concentrations and only slight increases in IL-6 and TNF-α were recorded within the first eight hours after infection, which is in accordance with results of previous studies." (PMID 28245826, 2017). "In a rabbit ear-wound model, mixed species infection of S. aureus and P. aeruginosa caused an increased expression of the pro-inflammatory cytokines IL-1β and TNF-α, indicating a higher inflammatory response compared to single species infection." (PMID 28421166, 2017). "Tumor necrosis factor (TNF) is a pleiotropic cytokine that is transcriptionally activated in response to a variety of stimuli during inflammation, infection, and stress." (PMID 28824652, 2017). "Possible reasons for these results include reactivation of LTBI in the early period of TNF antagonist therapy, and possible de novo infection with TB in the late period of long-term TNF therapy." (PMID 28743918, 2017). "Taken together, the present results suggest that inflammation in the hippocampus, caused predominantly by TNFα signaling, contributes to hyperexcitability and acute seizures after TMEV infection." (PMID 28497109, 2017). "We observed an induction of TNF-α secretion in response to H37Rv infection (1.48-fold increase as compared to unifected, untreated)." (PMID 29067283, 2017). "In fact, during the early hyperdynamic phase of infection, a proinflammatory state is heavily mediated by neutrophils, macrophages and monocytes with release of inflammatory cytokines, such as tumor necrosis factor-α (TNF-α) and interleukin-1 and -6." (PMID 28169298, 2017). "Overall, this study reveals a mechanism by which distinct viral genomic products determine cell fate upon infection by taking advantage of the dual functions of TNFα to perpetuate both virus and host." (PMID 28986577, 2017). "Macrophages play important roles in host defense to infection, repair of damaged tissue, and secretion of pro-inflammatory cytokines such as TNF-α and IL-6 to modulate inflammatory response." (PMID 28397806, 2017). "When naive THP-1 macrophages were stimulated with MVs obtained after infection, the amounts of TNF-α released were almost identical to the amounts released when stimulated with bacterial MVs only." (PMID 29132302, 2017). "Treatment of animals with anti-TNFα antibodies leads to severe pathology due to impaired formation of multicellular pathological lesions at the foci of infection (Mastroeni, Skepper and Hormaeche 1995)." (PMID 28087648, 2017). "Proteinase-activated receptor-2 has been shown to be a modulator of innate and adaptive immunity during infections, helping macrophage differentiation toward a pro-inflammatory phenotype, favoring mainly TNF production." (PMID 29230224, 2017).
infection (continued). "In line with the severity of infection, the levels of TNF-α, IL-6, and IFN-γ were significantly higher in the Wt-immunized group than in the Δhfq-immunized group." (PMID 28727722, 2017). "Neonatal mice likewise have an attenuated early inflammatory response to infection compared to adults, including a diminished upregulation of tumor necrosis factor alpha (TNFα)-related genes." (PMID 28224121, 2017). "To investigate the effect of TNF on the infection of human astrocytes by T. cruzi, we used the U-87MG astrocyte cell lineage." (PMID 28877735, 2017). "The adjuvant effect was inherently preserved with i.t. infection, albeit the systemic cytokine response after i.t. application was slightly inferior to i.v. infection as assessed by levels of serum TNF-α." (PMID 28637010, 2017). "Three days after infection, the IL-6 and TNF-α levels in serum of mice infected by X4550(pYA3334-SspH2-EscI) decreased, while those in mice infected with X4550(pYA3334-SspH2) and X4550(pYA3334) significantly increased (P < 0.05)." (PMID 28468643, 2017). "Correspondingly, high-dose infection results in elevated absolute numbers of double IFN-γ/TNF producers, especially among the inflationary CD8+ T cells." (PMID 29367854, 2017). "Supporting a dose-dependent relationship, serum levels of active TNF-α were reduced below detection limit early after infection with a 100-fold lesser inoculum of 5 × 104 CFU." (PMID 28445131, 2017). "The infection of microglia with P. gingivalis also significantly increased the secretion of IL-6 and TNF-α, and the accumulation of NO metabolites." (PMID 28924232, 2017). "More mechanistic properties have been described for TNF-α inhibitors to enhance development of an active infection with Mycobacterium Tuberculosis." (PMID 29104241, 2017). "Unregulated inflammation induced by infection or trauma results in excessive production of inflammatory cytokines, such as tumor necrosis factor (TNF), interferon-γ (IFN-γ), and interleukins (IL-1β, IL-6, etc.)." (PMID 28620379, 2017). "TNF-α and IL-1β, in particular, are key mediators of the signal transduction initiating immediate immune cell activity upon release from the site of infection." (PMID 28572772, 2017). "Our findings show that exercise suppresses infection-induced inflammation, as indicated by reductions in the levels in inflammatory cytokines (IL-12, TNF-α, IFN-γ,) and in another inflammation marker (NO)." (PMID 28572772, 2017). "Blood was collected before (day −10) and during infection (day 28) to evaluate levels of anti-TNF-α antibodies." (PMID 29184553, 2017). "By day 5, the infection progressed to high bacterial loads in the organs of anti-TNFα-treated mice, while mice treated with control IgG were able to better restrain bacterial growth." (PMID 28087648, 2017). "In this context, it is conceivable that the enhanced release of IL-12, TNF-α, IL-1β, and IL-6 by ΔesxB infection likely promotes a robust Th1 and Th17 response, whose crucial role in the immunity against S. aureus has been demonstrated by several studies." (PMID 28785545, 2017). "At 24 h after infection, the expression of cytokines and chemokines (i.e., TNF-α, IL-1β, IL-6, and IL-10) was evaluated by using ELISA." (PMID 28615695, 2017). "The analysis of the levels of proinflammatory cytokines in geldanamycin-treated mice revealed a significant reduction in TNF-α, IL-6, and IL-1α levels on days 2, 4, or 7 after infection compared with the vehicle-treated and oseltamivir-treated mice." (PMID 28664154, 2017). "Our data demonstrate that TNF-α blockade induces potent suppression of post-treatment pericystic inflammation in a natural infection model of NCC." (PMID 29190292, 2017). "To assess to what extent this novel anti-TNF strategy would affect immunity against infectious agents, we used two experimental models of infection, with L monocytogenes and M. tuberculosis." (PMID 29184553, 2017).
infection (continued). "Compared to mock infected islet cells, cell culture supernatant levels of TNFα were elevated at days 1, 3, and 7 post-infection." (PMID 29258547, 2017). "This interaction then leads to decreased production of IL-12 and TNF-α by activated macrophages, thereby inhibiting NO production and favoring infection." (PMID 29379503, 2017). "Upon pathogen recognition, macrophage-derived cytokines such as TNF-α, IL-1α and IL-1β trigger the response to local infection by activating lung epithelial cells." (PMID 28931863, 2017). "Animal and human studies of intracellular pathogens have extensively evaluated polyfunctional CD4+ T cells producing multiple pro-inflammatory cytokines (IFN-γ, TNF-α, and IL-2) as a possible correlate of protection from infection and disease." (PMID 29051764, 2017). "IAV-induced MMP-9, TNF, and IL-6 in lungs of MALT1-deficient mice are significantly lower than in wild-type mice after intratracheal infection." (PMID 29018444, 2017). "Whereas the interferons and their receptors appear to be major regulators of viral immune response, lipopolysaccharide, IL1β and TNF are the major regulators of responses activated by infection with M. haemolytica or M. bovis." (PMID 29263411, 2017). "In anti-TNFα-treated mice both ampicillin and ciprofloxacin prevented the uncontrolled escalation of the infection and induced a steep decline in viable bacterial numbers to levels similar to those observed after treatment of control animals." (PMID 28087648, 2017). "Proinflammatory early response cytokines IL-6 and TNF-α were only detectable in a significant amount whenever infection was present." (PMID 29348965, 2017). "TNF-α stimulates the production of interleukins that participate in the response to infection or injury, and IL-1β acts on macrophages to release IL-6 and IL-8 related to the pathogenesis of various inflammatory diseases." (PMID 28086859, 2017). "TNF plays an essential role in control and containment of intracellular pathogens, recruiting inflammatory cells to the area of infection and stimulating the formation and maintenance of granulomas that physically contain infection." (PMID 28146077, 2017). "We found a significant increase in expression of both hippocampal mRNA and protein levels of TNFα after TMEV infection that was coincident with focal and generalized seizure activity recorded by video-electroencephalography (vEEG)." (PMID 28497109, 2017). "Specifically, pro-inflammatory cytokine (e.g. IL-1α, MIP, and TNFα) levels rise, enhancing neutrophils migration to the infection site." (PMID 29117213, 2017). "In studies using a low multiplicity of infection in peripheral blood mononuclear cells, a slight delay was observed in the induction of TNF-α expression compared to the inflammatory response." (PMID 28331079, 2017). "In different time-points, the infection of 129sv mice was characterized by significant neutrophil recruitment, oedema formation, and the production of TNF-α, MIP-1α, IL-1α, MCP-1, LTB4, PGE2, and α-defensin-1 in the lungs." (PMID 29247243, 2017). "In the kidney, elevated TNFα level was found at day 2 post-infection stimulated by WT CLIB, and the quantity of this cytokine decreased at the later time point." (PMID 28713338, 2017). "siTIPE2 infection exacerbated the increased TNF-α and IL-6 concentrations, while Ad-TIPE2 infection reversed the increased TNF-α concentration in differentiated THP-1 cells under high glucose conditions (50 mmol/L)." (PMID 28626770, 2017). "Overexpression of IL-32γ resulted in significant increases in TNFα and IL-8 mRNA expression and protein production after infection with either Leishmania species in comparison with egfp transfected control cells." (PMID 28241012, 2017). "MCs degranulate and release inflammatory mediators such as TNF-α after infection and recruit polymorphonuclear leukocytes (PMNs) to the site of infection." (PMID 28428784, 2017).
infection (continued). "In the mouse model of infection, the influence of TNF-α in controlling bacterial growth only becomes apparent several days after inoculation." (PMID 28069818, 2017). "Using J774A.1 mouse macrophages, the effects of Dox on protein and mRNA levels of IL-1β and TNF-α were investigated after infection with live or sonicated Leptospira interrogans serovar Lai strain Lai (56601)." (PMID 28791016, 2017). "Concentrations of IL-2, IFN-γ, and TNF-α rapidly increased in the early stage of infection and reached to a peak within the first week." (PMID 28445973, 2017). "ADAM17 is regarded as a first line of defense against injury and infection, by releasing tumor necrosis factor α (TNFα) to promote inflammation and epidermal growth factor (EGF) receptor ligands to maintain epidermal barrier function." (PMID 27256961, 2017). "In contrast, in BALF, the major difference between strains was a lag in onset of the IFN-α or TNF-α maximum levels in the Finistere strain infection." (PMID 28241868, 2017). "ICS-assays revealed the presence of APP-CCE specific CD4+CD8αdim IL-17A-producing T cells in blood and lung tissue in most infected animals during the acute and chronic phase of infection and a minor fraction of these cells co-produced TNF-α." (PMID 28166835, 2017). "During tissue injury or infection, M1 macrophages produce a series of proinflammatory cytokines such as IL-6, TNF-α, ΝΟ and ROS." (PMID 28804688, 2017). "Intracellular staining of selected cytokines revealed that ECTV-infection also reduced the percentage of cells producing TNF-α and IL-12p40/p70." (PMID 29312229, 2017). "Infection of AMs in vitro with virulent mycobacteria higher levels of TNF than AMs infected with attenuated mycobacteria.Higher TNF production correlates with increased growth rate of mycobacteria." (PMID 28507549, 2017). "The pathogen was, in our case, Staphylococcus aureus, which showed the frequent infection secondary to receiving TNF-α inhibitors." (PMID 28179019, 2017). "Based upon above observations, we postulate that the differentiation of mDC was activated following initial SFTSV infection, but quickly mitigated by high titers of virus and inflammatory cytokines such as TNF-α and IL-6." (PMID 28747721, 2017). "Cytokines such as TNF-α, IL-1β, and IL-6 play key roles in various inflammatory processes, such as the acute-phase reaction, tissue damage, and infection." (PMID 28524081, 2017). "TNFα neutralization induced the expected exacerbation of the infection in the spleens and livers (Mastroeni, Villarreal-Ramos and Hormaeche 1992; Mastroeni, Skepper and Hormaeche 1995)." (PMID 28087648, 2017). "HK-Pg infection of BMM induced similar levels of TNFα, IL-12p70, IL-6, IL-10, and IFNβ compared to infection with viable P. gingivalis." (PMID 28824884, 2017). "The systemic inflammatory response to pathogen infection, local tissue injury or other trauma is mediated by pro-inflammatory cytokines, mainly interleukin 1β (IL-1β), interleukin-6 (IL-6) and tumor necrosis factor (TNF)." (PMID 29185442, 2017). "Reduced levels of TNF-α in neonatal monocytes after infection or challenge with bacteria or bacterial PAMPs (such as LPS) are a matter of debate with most studies indicating a bias towards reduced TH1 cytokine production in CBMO." (PMID 28793310, 2017). "Infection induced interleukin-1β, interleukin-6, tumor necrosis factor α, and ectopic trypsin in mouse lungs in a dose- and time-dependent manner." (PMID 27714503, 2017). "Physicians should be aware of secondary infections in the application of TNF-α inhibitors, even with proper usage." (PMID 28179019, 2017). "Neutralization of TNF-α by an αTNF-α antibody reduced apoptotic PICD in PBMO four-fold (p < 0.05 vs. infection with E. coli)." (PMID 28793310, 2017). "Recent studies have shown that CX3CR1+ monocytes can regulate learning and learning-dependent dendritic spine remodeling via TNF-α following infection with poly (I:C), a synthetic analog of double-stranded RNA." (PMID 28848542, 2017).